EGFR (epidermal growth factor receptor)
Diseases named in the same sentence as EGFR in open-access papers (continued):
Sharing a sentence is not in itself a finding about the gene and the disease.
gastric cancer (continued). "Presently, much of the available knowledge regarding EGFR and ERBB2 expression as well as their biological function in gastric cancer has come from countries other than China." (PMID 21689422, 2011). "For instance, E-cadherin, EGFR, VEGF and alpha, beta and gamma catenins have been found to distinguish the diffuse from intestinal type of gastric cancer." (PMID 27030788, 2011). "Taken together, these results suggested that propranolol enhanced the sensitivity of gastric cancer cells to radiation through the inhibition of β-ARs and the downstream NF-κB-VEGF/EGFR/COX-2 pathway." (PMID 20977754, 2010). "The present study demonstrates for the first time that β-adrenergic inhibition can enhance the effect of radiotherapy on gastric cancer cells in vitro through the downregulation of NF-κB and modulation of downstream COX-2, EGFR and VEGF gene expression." (PMID 20977754, 2010). "Adding the drug will enhance the sensitivity of gastric cancer cells to radiation through the inhibition of β-ARs and the downstream NF-κB -VEGF/EGFR/COX-2 pathway." (PMID 20977754, 2010). "Epidermal growth factor receptor expression was a prognostic factor in our study, but the prognostic role of EGFR in gastric cancer needs to be further elucidated." (PMID 19259093, 2009). "In this study, we demonstrated that EGFR, HER2, and TOP2A were overexpressed and amplified in gastric carcinomas from Chinese patients; similar results were observed in Western countries and in other Asian countries." (PMID 19061514, 2008). "This study documented alterations in protein expression and gene copy number for EGFR, HER2, and TOP2A in Chinese patients with gastric carcinoma." (PMID 19061514, 2008). "A combined investigation of the gene status of EGFR, HER2, and TOP2A should facilitate the identification of a target therapeutic regimen for gastric carcinoma patients." (PMID 19061514, 2008). "In the current study, EGFR, HER2, and TOP2A gene copy numbers and corresponding levels of protein expression in Chinese gastric carcinomas were determined by FISH and immunohistochemistry(IHC), respectively." (PMID 19061514, 2008). "Herein, we investigated the gene status of EGFR, HER2, and TOP2A in Chinese gastric carcinoma patients." (PMID 19061514, 2008). "ER-α36 can interact with epidermal growth factor receptor (EGFR) to activate downstream mitogen-activated protein kinase (MAPK) signaling, but the detailed mechanism in gastric cancer remains unclear." (PMID 42121888, 2026). "In gastric cancer, molecular effects of HDACi on the expression of EGFR have not been investigated so far." (PMID 39864337, 2025). "Multiple oncogenic and inflammatory pathways regulate PD-L1 expression in digestive system cancers including the EGFR/ERK signaling axis in esophageal squamous cell carcinoma, the JAK/STAT pathway in gastric cancer, and the ERK/MAPK pathway in hepatocellular carcinoma." (PMID 40874227, 2025). "The data suggest that EGFR is an indispensable molecule in the process of ACh-stimulated gastric cancer cell proliferation; however, the exact mechanism of action between CHRM3 and EGFR is still unclear in gastric cancer." (PMID 41516199, 2025). "Although EGFR has not yet been reported as an Ephrin A1-interacting partner, it has been known to be important for gastric cancer progression." (PMID 39838173, 2025). "Human epidermal growth factor receptor 2 (HER2), a member of the epidermal growth factor receptor (EGFR/HER) family, is a transmembrane tyrosine kinase receptor that is overexpressed in approximately 20–30% of breast and gastric cancers, as well as in subsets of other solid tumors." (PMID 41221272, 2025). "Gastric cancer cell line NCI-N87 expressed high level of HER2 and EGFR, and HER2 and EGFR cell surface level were very close, indicating that these EGFR and HER2 had great chance to exist on cell surface in the form of HER2/EGFR heterodimer upon ligand bindings." (PMID 38982548, 2024).
gastric cancer (continued). "Moreover, the extract targets key proteins, including EGFR, SCR, and IL6, to suppress the progression of gastric cancer, thereby synergistically inhibiting cancer development." (PMID 38611946, 2024). "A phase I open-label, non-randomized study (NCT03618381) is currently evaluating the safety and efficacy of EGFR-targeting CAR-T cells in patients with advanced solid tumors, including esophageal cancer and gastric cancer in children and young adults at Seattle Children's Hospital." (PMID 39417449, 2024). "Other mAbs and EGFR tyrosine kinase inhibitors alone do not show significant advantages in the treatment of advanced gastric cancer." (PMID 36674593, 2023). "Moreover, knockdown of LAMC2 was able to inhibit EGFR phosphorylation as well as its downstream targets ERK and AKT in pancreatic, anaplastic thyroid carcinoma, and gastric cancer cells." (PMID 37542131, 2023). "Thus, EV-mediated translocation of EGFR to the plasma membrane of liver stromal cells activated HGF/c-Met signaling, facilitating gastric cancer cell invasion and liver seeding." (PMID 37350937, 2023). "Using a combination of high-throughput virtual screening and in vitro analysis, we found that compound C3 from the ChemBridge small molecule library is a lead candidate that selectively targets EGFR and HER2 to stop cell growth in cell culture models of gastric cancer." (PMID 38186572, 2023). "and found to exert an antineoplastic effect in gastric cancer cells MKN-45 by inducing apoptosis and cell cycle arrest and in AGS cells by suppressing insulin-like growth factor receptor (IGFR), epidermal growth factor receptor (EGFR) expression and blocking PI3K/Akt/mTOR pathways." (PMID 36193068, 2022). "Relevant to both OSCC and EBV+-gastric cancer, JAK2/STAT1 signaling has been shown to mediate respectively EGFR- or IRF-1, IFNγ-induced upregulation of the programmed cell death-ligand 1 (PD-L1), an inhibitor of T-cell-mediated tumor cytotoxicity as discussed later in this review." (PMID 35844493, 2022). "ILK and EGFR are both the significantly depeleted genes in this screen, which means the combinational inhibition of them and FGFR can ideally boost the efficacy of the treatment to gastric cancer." (PMID 35372044, 2022). "KEGG enrichment analysis showed that the target genes may be involved in gastric cancer through effects on the MAPK signaling pathway, proteoglycan in cancer, EGFR tyrosine kinase inhibitor resistance, and other biological pathways." (PMID 36200190, 2022). "The expression of EGFR and HER-2 in patients with gastric cancer." (PMID 35984169, 2022). "MiR-1296-5p has been found to inhibit gastric cancer progression by suppressing CDK6 and EGFR." (PMID 35962353, 2022). "Therefore, β-elemene can reverse EMT in MDR gastric cancer cells by inhibiting the transcription factors ZEB1 and ZEB2 and through the miR-1323/Cbl-b/EGFR pathway." (PMID 34641334, 2021). "The lack of commercially available EGFR-amplified GEA cancer cells lines has so far hindered the pre-clinical testing of EGFRi in gastric cancer." (PMID 33199443, 2021). "The aim of this study was to assess the antitumor activity of duligotuzumab, an anti HER3/EGFR antibody or ipatasertib, an AKT inhibitor, combined with trastuzumab in a panel of HER2-positive human gastric cancer cells (GCC), and the efficacy of such combinations in HER2-resistant cells." (PMID 34066144, 2021). "Thus, IHC expression of 2+ and 3+ can be useful in triaging patients for more comprehensive testing of EGFR CNV by ISH or polymerase chain reaction as is the current practice for detection of HER2 amplification in breast and gastric cancer." (PMID 34912708, 2021). "Our previous study demonstrates that CMTM3 suppresses metastasis of gastric cancer through the STAT3/EMT signaling pathway by interacting with Rab5 to facilitate EGFR degradation and CMTM3 may serve as a prognostic and predictive biomarker in gastric cancer." (PMID 34560882, 2021).
gastric cancer (continued). "We have found that Cbl-b could inhibit cell proliferation by ubiquitinating the survival signal of the epidermal growth factor receptor (EGFR) pathway in lung and gastric cancer cells." (PMID 32435620, 2020). "Various randomized controlled trials (RCT) (mainly without the stratification based on EGFR status) have been conducted to study the efficacy of the adding molecular-targeted therapies to chemotherapeutics for the treatment of advanced gastric cancer." (PMID 32850413, 2020). "More recently, additional studies have indicated that propranolol could enhance the sensitivity of gastric cancer cells to radiotherapy by inhibiting beta-adrenoceptors, NF-κB expression, and its downstream genes: VEGF, EGFR, and COX-2." (PMID 33193702, 2020). "Six of them (β-catenin, C-MYC, CXCL13, DC-SIGN, EGFR, and PIM2) are consistently described as oncogenes according to the literature, and are overexpressed at the protein or mRNA level in gastric tissue among infected children and gastric cancer patients." (PMID 32117120, 2020). "It is known that intestinal-type gastric cancer is distinguished by overexpression of HER2 while diffuse-type gastric cancers are characterized by amplification of c-met receptor and aberrations in the EGFR kinase pathway." (PMID 33379302, 2020). "In vitro, EVs from SGC-7901 gastric cancer cells delivered GFP tagged EGFR to non-cancerous primary mouse liver cells resulting in a 3-fold increase in both EGFR expression and HGF secretion." (PMID 33143170, 2020). "The mutation, overexpression, and amplification of c-Met are often observed in cancers such as gastric cancer and non-small-cell lung cancer (NSCLC) at different stages and even after treatment with epidermal growth factor receptor (EGFR) tyrosine kinase inhibitors (TKIs)." (PMID 32028611, 2020). "This schematic diagram shows our research content very intuitively: After being stimulated by RANKL, the transmembrane proteins EGFR and RANK form a complex with Cav-1 on the lipid raft platform, which further activates downstream signaling pathways and ultimately promotes gastric cancer migration." (PMID 31933009, 2020). "Third, although revealed in previous studies 16, direct evidence of how CD148 dephosphorylate the Y1173, Y1068, and Y1092 on EGFR was lacked in gastric cancers." (PMID 32201537, 2020). "Similarly, earlier work has demonstrated that EGFR was co-immunoprecipitated with endogenous LAPTM4B and LAPTM4B overexpression correlates with EGFR activation in gastric cancer cells." (PMID 30940109, 2019). "Therefore, we concluded that GPAA1 promotes the interaction between EGFR and ERBB2 and the signalling of the downstream promoter of proliferation—Akt—to enhance the uncontrolled growth of gastric cancer cells." (PMID 31118109, 2019). "Apart from various reports about the prognostic value of EGFR members separately in gastric cancer, there is not any report about the probable correlation between ErbB1 and ErbB3 co-expression and gastric cancer prognosis." (PMID 30621788, 2019). "In order to explore whether in vitro experimental results were consistent with the pathogenesis of gastric cancer, we examined the expressions of MICAL‐L2 and EGFR in gastric cancer tissue and its adjacent tissue by a tissue microarray (30 paired cases)." (PMID 31034158, 2019). "Although, there are various reports about the prognostic value of EGFR members separately in gastric cancer, there is not any report about the probable correlation between ErbB1 and ErbB3 co-expression and gastric cancer prognosis." (PMID 30621788, 2019). "In the present study, we have not used inhibitors or si/shRNA for EGFR to inhibit EGFR signaling in gastric cancer cells." (PMID 31491956, 2019).
gastric cancer (continued). "This study aimed to describe the prognostic importance of epidermal growth factor (EGFR), phosphatase and tensin homolog (PTEN), human EGF receptor-2 (HER-2), and insulin-like growth factor 1 receptor (IGF-1R) in gastric cancer patients treated with postoperative chemoradiation therapy." (PMID 31318186, 2019). "Thus, activation of PI3K-mTOR signaling in CDH1-deficient gastric cancer cells might be the result of multiple signal transduction aberrations including lack of suppression of ligand-mediated EGFR activation or lack of negative feedback inhibition of the PI3K–Akt axis via reduced PTEN levels." (PMID 29468433, 2018). "The results of western blot from patients also showed there was obvious negative correlation between p-EGFR and integrin β4 in gastric cancer patients." (PMID 29618949, 2018). "Overexpression of RTKs has been found in a variety of human cancers: EGFR in GBM, lung, esophageal and thyroid cancer; HER2/ErbB2 in lung, bladder, breast and gastric cancer; and MET in lung and gastric cancer." (PMID 29455648, 2018). "Our study verified the correlation between CT texture features and immunohistochemical biomarkers, including E-cadherin, Ki67, VEGFR2 and EGFR, in gastric cancers, which has not been previously reported by any study until now." (PMID 30087428, 2018). "Epidermal growth factor receptor (EGFR)-directed antibodies cetuximab or panitumumab have failed to provide a significant benefit in non-molecularly selected gastric cancer patients." (PMID 28852882, 2018). "None of the CT texture features differed significantly between gastric cancers with positive EGFR expression and those with negative EGFR expression." (PMID 30087428, 2018). "The deep failure of anti-EGFR drugs in gastric cancer can be explained mainly with the lack of a proper patient selection." (PMID 30205505, 2018). "In fact, while in colon cancer the EGFR status is not usually analyzed as the wild type receptor activity is considered critical for tumor growth, no such data are available in gastric cancer." (PMID 28915702, 2017). "To investigate whether our experimental findings could be relevant to the pathogenesis of gastric cancer in humans, we examined CD24 and EGFR expression patterns in high and low degree differentiated gastric cancers." (PMID 26830684, 2016). "If these findings can be translated into gastric cancer settings, patients with high expression of MET, FGFR1 and ERBB2 may exhibit EGFR therapeutic resistance." (PMID 27738318, 2016). "In contrast, monoclonal anti-EGFR antibodies are currently not indicated for the treatment of gastric cancer, although they are used for patients with metastatic colorectal or head and neck carcinomas." (PMID 27387915, 2016). "Although CD24 was detected on the cytoplasm in gastric cancer cells as other report suggested, we were surprised to observe that CD24 was localized to the cell membrane, where it was partially co-localized and interacted with EGFR." (PMID 26830684, 2016). "The contents of CD24 and epidermal growth factor receptor (EGFR) in gastric cancer cells (SGC-7901 and BGC-823) and non-malignant gastric epithelial cells (GES-1) were evaluated by Western blotting assay." (PMID 26830684, 2016). "Higher expression levels of RTKs were detected in gastric cancer tissues compared with normal tissues, and some RTKs (e.g., EGFR, HER2, c-MET and vascular endothelial growth factor receptor) have been known to induce invasion, metastasis and EMT in gastric cancer." (PMID 27121055, 2016). "Interestingly, in SGC-7901 gastric cancer cells, CD24 was shown to maintain the expression of EGFR through a RhoA-dependent manner." (PMID 26830684, 2016). "The prevalence of EGFR and HER2 co-amplification has been reported as low (<0.5 %), albeit studies analysing concurrent EGFR and HER2 GCN changes are few and none have been carried out after the novel molecular subtypes of gastric cancer were published." (PMID 27387915, 2016).
gastric cancer (continued). "LINC00152 could directly bind to EGFR and activate EGFR signaling pathway and FENDER could suppress cell invasion and migration by downregulating FN1 and MMP2/MMP9 expression in gastric cancer." (PMID 27966444, 2016). "Moreover, analysis of gastric cancer specimens also showed a positive correlation between CD24 and EGFR expression." (PMID 26830684, 2016). "Our previous study demonstrated that PKG II could inhibit the activation of some key members of the RTK family, including EGFR, VEGFR, PDGFR and IGF-1R, and the consequent signal transduction in gastric cancer cells." (PMID 27147579, 2016). "Therefore, drugs that target EGFR and HER-2 are expected to improve the therapeutic efficacy of gastric cancer treatments." (PMID 26728266, 2016). "Analysis in strata according to location revealed that the prognostic impact of EGFR was significant in esophageal cancer (p = 0.014), but non-significant in gastric cancer." (PMID 26844548, 2016). "Unfortunately, neither the anti-EGFR monoclonal antibodies (cetuximab and panitumumab) nor the inhibitor (lapatinib) antagonizing the downstream EGFR tyrosine kinase significantly improved the survival of patients with advanced gastric cancer." (PMID 26880889, 2016). "The expression of NTR1 and its relationship with EGFR and β-catenin in gastric cancer have not been reported." (PMID 26215716, 2015). "In the present study, we observed that gefitinib, an epidermal growth factor receptor (EGFR) inhibitor, activated autophagy in the gastric cancer cells, as indicated by LC3-positive puncta and increased the levels of the autophagosome-bound form of LC3, LC3 II." (PMID 25652880, 2015). "Heterogeneity is common for the biomarkers HER2, CCND1, EGFR and MYC in gastric cancer and may therefore limit treatment decisions based on the analysis of a single clinical biopsy." (PMID 25649416, 2015). "The aim of this study is to investigate the methylation status at CpG sites of the promoter of EGFR in gastric cancer tissues and corresponding noncancerous tissues." (PMID 25959250, 2015). "In phase III EXPAND trial, the addition of cetuximab (chimeric monoclonal anti-EGFR antibody) to standard cisplatin and capecitabine did not improve progression free survival in patients with advanced gastric cancer." (PMID 25945346, 2015). "Moreover, gastric cancer patients with synchronous expression of EGF and EGFR have been reported to have a poor prognosis." (PMID 25729328, 2014). "Therapeutic targeting of EGFR and HER-2 could be a promising line of research in canine gastric cancer." (PMID 24454858, 2014). "There are many novel compounds available today targeting different molecular pathways of gastric cancer such as HER2, EGFR, MET, FGFR, and PI3K/MTOR, which could potentially be used for the treatment of gastric adenocarcinomas." (PMID 25025766, 2014). "Moreover, HER2 can be therapeutically targeted with a monoclonal antibody trastuzumab and a small molecule HER2/EGFR (epidermal growth factor receptor) inhibitor lapatinib in the treatment of HER2 overexpressing breast and gastric cancers." (PMID 24687970, 2014). "Further study in our laboratory showed that PKG II could inhibit the proliferation of gastric cancer cell lines and block EGF induced signal transduction of MAPK/ERK-mediated pathway through preventing the activation of EGFR by EGF." (PMID 23613900, 2013). "Based on the results above, no more clinical trials of anti-EGFR monoclonal antibody in gastric cancer will be carried out." (PMID 24330856, 2013). "TFF3 has also been shown to induce phosphorylation of epidermal growth factor receptor (EGFR), which may in turn activate the cell survival signaling molecules PI3K and Akt in a colonic epithelial cell line (HT-29) and a gastric cancer cell line (AGS)." (PMID 24204940, 2013).